GCH1 (GTP cyclohydrolase 1)
Description:
Positively regulates nitric oxide synthesis in umbilical vein endothelial cells (HUVECs). May be involved in dopamine synthesis. May modify pain sensitivity and persistence. Isoform GCH-1 is the functional enzyme, the potential function of the enzymatically inactive isoforms remains unknown.
Synonyms: DYT5; GCH; GTPCH1; DYT5a; DYT14; GTP-CH-1; HPABH4B
Tractability: Small molecule: a structure with a bound ligand is known. PROTAC: ubiquitination databases record sites on it; its protein half-life has been measured.
Chemical probes: AXSP0056 (high quality)
Safety:
Unwanted effects reported when the protein is acted on. In parentheses: how it was acted on, where the effect was seen, and who reports it.
Hypertension (inhibition; source: AOP-Wiki)
Gene: Protein-coding gene on chromosome 14 (54,842,008 to 54,903,280, reverse strand). Ensembl gene ENSG00000131979.
Subcellular location: Cytoplasm; Nucleus
Subcellular location (Human Protein Atlas): Nucleoplasm; Cytosol; Nuclear membrane
Pathways (Reactome):
Metabolism: Tetrahydrobiopterin (BH4) synthesis, recycling, salvage and regulation
Gene Ontology:
Molecular function: GTP binding; GTP cyclohydrolase I activity; GTPase activity; identical protein binding; mitogen-activated protein kinase binding; protein binding; protein homodimerization activity; zinc ion binding
Biological process: dopamine biosynthetic process; neuromuscular process controlling posture; positive regulation of nitric-oxide synthase activity; pteridine-containing compound biosynthetic process; regulation of blood pressure; regulation of removal of superoxide radicals; response to lipopolysaccharide; response to tumor necrosis factor; response to type II interferon; tetrahydrobiopterin biosynthetic process; nitric oxide biosynthetic process; response to pain; positive regulation of heart rate; pteridine-containing compound metabolic process; tetrahydrobiopterin metabolic process; tetrahydrofolate biosynthetic process
Cellular component: cytoplasm; cytoplasmic vesicle; cytosol; nuclear membrane; nucleoplasm; nucleus; protein-containing complex; neuron projection terminus
Genetic constraint (gnomAD): Loss-of-function variants: 4 observed, 10.18 expected, observed/expected ratio (o/e) 0.39, 90% interval 0.19 to 0.9. The synonymous counts are far from expectation, so gnomAD's model fits this gene poorly and the ratio says little. Missense variants: 176 observed, 200.38 expected, observed/expected ratio (o/e) 0.88, 90% interval 0.78 to 1. Synonymous variants: 115 observed, 86.48 expected, observed/expected ratio (o/e) 1.33, 90% interval 1.14 to 1.55.
Gene-disease validity (ClinGen):
ClinGen rates the evidence that GCH1 causes each of these diseases.
GTP cyclohydrolase I deficiency (semidominant): Definitive. A disease characterized by a deficiency in GTP cyclohydrolase I, which leads to a consequent reduction in BH4 and reduces the activity of three BH4-cofactor dependent enzymes - phenylalanine hydroxylase, tyrosine hydroxylase, and tryptophan hydroxylase.
Homologues: Orthologues: chimpanzee GCH1 (100% identical), macaque GCH1 (99% identical), pig GCH1 (93% identical), rat Gch1 (89% identical), mouse Gch1 (86% identical), dog GCH1 (84% identical), guinea pig GCH1 (81% identical), tropical clawed frog gch1 (78% identical), zebrafish gch1 (74% identical), Drosophila melanogaster Pu (64% identical), Caenorhabditis elegans cat-4 (55% identical).
Diseases named in the same sentence as GCH1 in open-access papers:
GCH1 is named in the same sentence as 180 diseases in open-access papers, as found by Europe PMC text mining. Sharing a sentence is not in itself a finding about the gene and the disease. The quoted sentences say what the papers report.
Dystonia (65 papers, 2009 to 2026). An abnormally increased muscular tone that causes fixed abnormal postures. "Disorders associated with PTS and GCH1 include phenylketonuria, abdominal obesity-metabolic syndrome, limb-girdle muscular dystrophy, Opitz-Kaveggia syndrome, dystonia, epilepsy, and autism spectrum disorder." (PMID 41158885, 2025). "GTP cyclohydrolase 1-Deficient Dopa-Responsive Dystonia (DYT-GCH1), first described in 1994, is an autosomal dominant combined dystonia, with childhood onset." (PMID 40584247, 2025). "Forty-five PD individuals (0.57%) carried 26 distinct (likely) pathogenic variants in nine dystonia-linked genes, most frequently in GCH1, followed by VPS16." (PMID 40672488, 2025). "Dopa‐responsive dystonia (DRD) encompasses a spectrum of rare, genetically and clinically diverse monogenic dystonias caused by variants in GCH1, TH, SPR, PTS, and QDPR genes." (PMID 40146714, 2025). "Analogously, parkinsonism is commonly seen in subtypes of dystonia caused by genes such as GCH1, TH, TAF1, ATP1A3, and PRKRA." (PMID 37304079, 2023). "TH is a well-established causative gene for DRD similar to GCH1, and mutations of TH and GCH1, resulting in deficiencies of the enzymes involved in the dopaminergic synthesis pathway, can present with dystonia and parkinsonism." (PMID 37304079, 2023). "KO mutant mice with mutations in the GTP cyclohydrolase 1 gene (gch1) used as models of DYT5 dystonia display abnormal movements and dystonic posture in the hindlimbs in parallel with tyrosine hydroxylase depletion in the striatum." (PMID 35955710, 2022). "This form of dystonia is much more severe than dopa-responsive dystonia caused by mutation in GCH1 gene, inherited in an autosomal dominant fashion." (PMID 35207493, 2022). "Dopa-responsive dystonia (DRD) is caused by an impaired dopamine biosynthesis due to a GTP-cyclohydrolase-1 (GCH1) deficiency, resulting in a combination of dystonia and parkinsonism." (PMID 35995805, 2022). "The first dopamine-related gene identified for dystonia was GCH1, encoding the rate-limiting enzyme in the pathway that converts guanosine triphosphate (GTP) to tetrahydrobiopterin (BH4), which is an essential cofactor for dopamine biosynthesis." (PMID 34305140, 2021). "First, DYT5 (DYT-GCH1, Segawa disease) is adopa-responsible dystonia (DRD) type caused by guanosine triphosphate cyclohydrolase 1 (GCH-1) deficiency, which is a rate-determining enzyme for dopamine production." (PMID 34867735, 2021). "Several previous studies have found that patients carrying mutations in dystonia-related genes, such as GCH1 and TH, displayed features of Parkinsonism in addition to dystonia." (PMID 33964895, 2021). "Heterozygous GCH1 variants decrease dopamine synthesis in nigrostriatal neurons, leading to childhood-onset, progressive, dopa-responsive dystonia." (PMID 34305140, 2021). "Clinically, IMPDH2-linked dystonia mimicks other dominantly inherited dystonias such as those caused by variants in GCH1, also an enzyme in the GTP-BH4 pathway." (PMID 34305140, 2021). "Although a dramatic response can be observed in patients with GCH1 mutations, some still have residual motor symptoms (females are more common), such as dystonia and parkinsonism." (PMID 32185155, 2020). "Patients with GCH1 mutations demonstrated reduced GCH1 activity, thus leading to decreased dopamine levels and resulting in dystonia (Nagatsu, Levitt, & Udenfriend, 1964)." (PMID 29484265, 2018). "We first describe the clinical, genetic and nigrostriatal dopaminergic imaging findings of DOPA-responsive dystonia pedigrees in which pathogenic GCH1 variants were identified in family members with adult-onset parkinsonism." (PMID 24993959, 2014). "Reduced penetrance of GCH1 pathogenic variants for the DOPA-responsive dystonia phenotype is a well-established feature." (PMID 24993959, 2014). "Clinically, alterations of GCH1 activity has been associated with bipolar disorders, depression, anxiety, dystonia and deafness." (PMID 22701688, 2012).
Dystonia (continued). "It is interesting to note that elevated expression of GCH1 has been implicated in mood disorders, while genetic polymorphisms or mutations in GCH1 have been associated with pain sensitivity, and dystonia, which are often associated with ASDs." (PMID 21556359, 2011). "GCH1 is known to cause dystonia and parkinsonism, independently or combined." (PMID 40672488, 2025). "Interestingly, previous screening studies of PD patients identified carriers of pathogenic variants in genes primarily linked to dystonia, most frequently GCH1." (PMID 40672488, 2025). "However, since the discovery of GCH1 in 1994, the first monogenic cause of dystonia to be identified, over 50 others have been reported and many more still causing combined syndromes." (PMID 40574302, 2025). "Regarding early onset inherited dystonia, in our cohort, we report three pediatric patients with homozygous GCH1 variants who displayed the classic phenotype of dopa-responsive dystonia and demonstrated a significant and sustained response to low doses of L-dopa." (PMID 40134721, 2025). "Although not frequently reported, a few studies have described hearing loss in dystonia, with 50% of a single GCH1 mutation-positive cohort reported to experience symptoms of hearing loss, as well as there being the rare but recognised X-linked dystonia deafness syndrome." (PMID 38512523, 2024). "The IMPDH2 reaction is flanked by HPRT1 products—also a dystonia-linked protein—upstream from GCH1." (PMID 34305140, 2021). "In this study, we assessed whether polymorphic variants in the GCH1 gene, in which mutations may cause dystonia, are associated with NSCL/P in a sample from the Polish population." (PMID 26215833, 2016). "Rare mutations in GCH1 lead to hyperphenylalaninemia or DOPA-responsive dystonia." (PMID 25369080, 2014). "According to a systematic review, 86% of heterozygous GCH1 carriers present with dystonia to a variable extent, either isolated or combined dystonia-parkinsonism, while 11% have only parkinsonism." (PMID 40672488, 2025). "Other genes found to be associated with isolated or combined dystonia include ANO3 (DYT24), TUBB4A (DYT4), GCH1 (DYT5a), TH (DYT5b), TAF1 (DYT3), PRKRA (DYT16), ATP1A3 (DYT12), SGCE (DYT11), KCTD17, and CACNA1A." (PMID 33051750, 2021). "Two patients (6.5%) had GCH1 gene mutations and were diagnosed with classic DRD, with dystonia beginning in the lower limbs, diurnal fluctuation, improvement by sleep or rest and a sustained response to L-dopa." (PMID 32185155, 2020). "In support of this finding, rare and common variants in GCH1, the most common genetic cause of DOPA-responsive dystonia, have also been shown to increase the risk of Parkinson’s disease." (PMID 32889528, 2020). "Some of these PSGs, such as GCH1 (GTP-cyclohydrolase I), are associated with Parkinsonism, dystonia, and phenylketonuria disease in humans." (PMID 33099628, 2020). "One form of dystonia Segawa disease, is known to be due to defects in the GTP cyclohydrolase encoding gene (GCH1) that encodes an enzyme required for neurotransmitter biosynthesis." (PMID 28516087, 2017). "A deficiency of GTP cyclohydrolase, encoded by the GCH1 gene, results in two neurological diseases: hyperphenylalaninaemia type HPABH4B and DOPA-responsive dystonia." (PMID 26215833, 2016). "DRD is frequently caused by heterozygous mutations in the guanosine triphosphate (GTP) cyclohydrolase 1 gene (GCH1), with this form of dystonia now referred to as DYT5." (PMID 24124602, 2013). "Contrary, loss of function mutations in the GCH1 gene results in decreased basal GCH1 expression, and is associated with DOPA-responsive dystonia (DRD)." (PMID 23421753, 2013). "Mutations in the GTPCH1 gene (GCH1) are associated with malignant phenylketonuria and hyperphenylalaninemia, as well as L-DOPA (Levodopa)-responsive dystonia." (PMID 22984419, 2012).
Dystonia (continued). "For six variants, segregation analysis revealed that the identified variant co‐segregated with the dystonia phenotype in the affected families, supporting its pathogenic role (EIF2AK2:p.Pro31Ser, EIF2AK2:p.Gly130Arg, THAP1:p.Ser51Arg, GCH1:p.Glu61*, SGCE:p.Met174Lys, SGCE:c.233‐1G>A:p.)?" (PMID 40533913, 2025). "The majority (n=43) were carriers of heterozygous variants in genes linked to dominantly inherited dystonia genes (ATP1A3, GCH1, SGCE, KMT2B, THAP1, TOR1A, and VPS16), while only one carrier of a homozygous PLA2G6 variant and one of compound-heterozygous PTS variants were identified." (PMID 40672488, 2025). "Considering that the previous dystonia panel did not include structural variations of GCH1 and TH and did not exclude variants related to Parkinsonism, we performed WGS to conduct a more detailed investigation." (PMID 40146714, 2025). "Mutations in some dystonia genes, such as THAP1 (DYT6), can cause both focal/segmental and generalized forms of the disease, while others (e.g., TH or GCH1) may even give rise to both isolated and combined dystonias." (PMID 28138320, 2016). "We subsequently showed, in a large cohort of patients with Parkinson’s disease without family history of DOPA-responsive dystonia, that rare GCH1 coding variants are associated with Parkinson’s disease and increase the disease risk by 7-fold on average." (PMID 24993959, 2014). "Loss-of-function mutations in GCH1 result in severe reduction of dopamine synthesis in nigrostriatal cells and are the most common cause of DOPA-responsive dystonia, a rare disease that classically presents in childhood with generalized dystonia and a dramatic long-lasting response to levodopa." (PMID 24993959, 2014). "Nevertheless it has been repeatedly reported, through analysis of brain tissue, CSF and urine, that even completely asymptomatic carriers of GCH1 mutations have abnormal metabolism of biopterins and dopamine, although to a lesser extent than DOPA-responsive dystonia cases." (PMID 24993959, 2014). "In contrast to the GCH1 PP haplotype leading to moderate reduction of BH4 availability and only after stimulation, loss of function mutations in the GCH1 gene causes reduced basal concentrations of BH4 and is associated with DOPA-responsive Dystonia (DRD)." (PMID 23421753, 2013). "Three adult male GCH1 mutation carriers in two families showed no symptoms of dystonia, although their female siblings/offspring had relatively severe DRD." (PMID 23762320, 2013). "In the present study, three male GCH1 mutation carriers had no symptoms of dystonia, although all of them were older than 36 years." (PMID 23762320, 2013). "In family 10, we found the GCH1 Ile135Thr mutation in the unaffected father and brother, both of whom had depression but not dystonia." (PMID 23762320, 2013). "Even in patients with pure Parkinsonism (without dystonia), the frequency of rare GCH1 variants were higher than in controls, indicating that variants in GCH1 may be associated with a higher risk of PD." (PMID 33964895, 2021). "We hypothesized that pathogenic variants in GCH1 could be found in subjects with Parkinson’s disease without a family history for DOPA-responsive dystonia." (PMID 24993959, 2014). "Parkinsonian features are frequently detected in patients with DOPA-responsive dystonia and family studies have shown that carriers of GCH1 mutations may develop adult-onset parkinsonism in the absence of dystonia." (PMID 24993959, 2014). "Another possibility is that GCH1 mutation carriers who do not develop symptoms of DOPA-responsive dystonia in childhood may have compensatory mechanisms that allow for normal nigrostriatal dopaminergic transmission." (PMID 24993959, 2014). "Our study expands this list to include dystonia by revealing that the +142C>T GCH1 5’UTR substitution detected in DRD patients is a functional mutation that reduces translational efficiency and likely leads to reduced wild type GCH1 protein levels, underlying manifestation of DRD." (PMID 24124602, 2013).
Dystonia (continued). "In humans, GCH1 is reported to be important for many diseases, including pain sensitivity, DOPA-responsive dystonia, hypertension, and Parkinson's disease 23-26." (PMID 41583517, 2026). "In the last decade, numerous genetic disorders have been reported to encompass in their phenotype recurrent episodes of dystonia and/or chorea (i.e., ADYC5, GCH1, and ATP1A3)." (PMID 40724495, 2025). "The most frequently implicated genes included the well‐established isolated and combined dystonia genes VPS16 (n = 17 index patients), THAP1 (n = 14), GCH1 (n = 13), SGCE (n = 12), GNAL (n = 8), and KMT2B (n = 8)." (PMID 40533913, 2025). "Another patient was a 65-year-old woman harbouring a heterozygous GCH1 deletion, who showed mild parkinsonian symptoms without signs of dystonia, and her daughter carrying the same GCH1 heterozygous mutation was suffered from DRD." (PMID 25181484, 2014). "We subsequently explore the hypothesis that GCH1 variants might be associated with an increased risk for Parkinson’s disease, even without a family history for DOPA-responsive dystonia, through examination of whole-exome sequencing data from a large cohort of cases and controls." (PMID 24993959, 2014).